NMT1 (N-myristoyltransferase 1)
Diseases named in the same sentence as NMT1 in open-access papers (continued):
Sharing a sentence is not in itself a finding about the gene and the disease.
tumor (continued). "Pharmacological inhibition of NMT1 using DDD85646 reduced tumor growth in vivo, and tumors from treated animals had increased apoptosis and expressed markers of lysosomal disfunction." (PMID 32686708, 2020). "NMT1 has exhibited numerous dominant functions, such as in vivo inhibition of tumor growth in NMT1 knockdowns and defective myelopoiesis in NMT1 knockdown mouse embryos (Kumar, Singh, Dimmock, & Sharma, 2011; Kumar & Sharma, 2015; Zhao & Ma, 2014)." (PMID 30848105, 2019). "Consistent with retarded tumor growth, the proportion of Ki67-positive cells was significantly lower in the NMT1 knockdown group." (PMID 30446635, 2018). "NMT1 knockdown decreased the CSC frequency supporting that tumor initiation ability was abrogated by NMT1 inhibition." (PMID 30446635, 2018). "It inhibited tumor growth in organoid, xenograft and cell models by targeting N-myristoyltransferase 1 (NMT1), disrupting visinin-like protein-3 (VILIP3) myristoylation and NFκB/Bcl-2 signaling, suggesting NMT1 as a potential biomarker and therapeutic target in HCC." (PMID 41050078, 2025). "To further explore the underlying mechanisms of hypoxia-mediated immune regulation, we selected representative immune activation- and immunosuppression-related molecules in the tumor microenvironment and analyzed their correlations with hypoxia scores and NMT1 expression." (PMID 40605065, 2025). "Previously, several studies have reported that NMT1 served as a tumor promotor in several tumors." (PMID 38654047, 2024). "Conversely, reduced NMT1 expression may relate to metabolic pathways (ascorbate and aldarate metabolism, starch and sucrose metabolism) and the TGF-beta signaling pathway, indicating that NMT1 might influence tumor cell metabolism and growth regulation." (PMID 38654047, 2024). "Notably, both the mRNA and protein expression level of NMT1 in the tumor tissues of patient #1 and patient #2 was higher than that in patient #3." (PMID 36617552, 2023). "Furthermore, in vivo experiments showed that HCC tumor xenografts were less sensitive to desloratadine when NMT1 expression was downregulated." (PMID 36617552, 2023). "There is a correlation between poor survival outcomes and high NMT1 levels in tumours." (PMID 37140999, 2023). "NMT1 also accelerated NSCLC tumor metastasis and resistance to cisplatin." (PMID 36551208, 2022). "Also, by liver conditionally knocking NMT1 out in mice (NMT1−/−, NMT1flox/flox: Alb-Cre), we observed that treating DEN/CCl4 was unable to cause obvious formation of tumor loci compared to the liver of control mice (NMT1+/+, Alb-Cre)." (PMID 34136404, 2021). "Therefore, inhibition of NMT1 prevents the myristoylation of Src, which can eliminate the tumourigenic capacity of Src, while also interrupting the synergistic effect of Src with AR in mediating tumour invasion." (PMID 37140999, 2023). "Concurrently, the NMT1 inhibitor PCLX-001, at a concentration of 0.1 μmol/L, reduces PD-L1 membrane localization on tumor cells by inhibiting CHP1 myristoylation, decreasing PD-L1 availability to interact with PD-1 on T cells." (PMID 40605065, 2025). "This paradoxical observation—where clinically high NMT1 expression is correlated with poor prognosis but lacks direct cell-autonomous tumor-promoting effects—prompts us to focus on noncell-autonomous mechanisms." (PMID 40605065, 2025). "NMT1 expression was analyzed in an HCC TMA consisting of 180 tumor tissues and 176 matched nontumor tissues." (PMID 36617552, 2023). "Furthermore, inhibition of the NMT1/VILIP3/NFκB/Bcl-2 regulatory axis was observed in the desloratadine-treated PDX#1 and PDX#2 tumor xenografts, as indicated by Western blot." (PMID 36617552, 2023). "Normal breast epithelial elements adjacent to tumor on the TMA were universally positive for NMT1 (1–2+) on a 0–2 scale, scored as 0—absent; 1+ weak/moderate staining; 2+ strong staining." (PMID 33398478, 2021).
tumor (continued). "NMT1 (but not NMT2) knockdown was shown to inhibit tumor growth, which can be rationalized by the fact that NMT substrates include proto-oncogenic Src-family kinases." (PMID 23824448, 2013). "Significant upregulation of NMT1 was observed in human HCC tissues compared with paired nontumor tissues, and high NMT1 expression was significantly associated with advanced pathological T-stage, tumor grade and tumor size." (PMID 36617552, 2023). "But, the effect of NMT1 knockdown on tumor invasion was not rescued might due to that the treatment time was not enough." (PMID 30446635, 2018).
infection (8 papers, 2010 to 2024). The state of being infected such as from the introduction of a foreign agent such as serum, vaccine, antigenic substance or organism. "We characterized the interaction of the Z matrix protein with NMT1 and NMT2 and found that during infection NMT1 has a predominant role for all Mammarenavirus tested." (PMID 39625987, 2024). "HAP1 NMT1ko were transfected with control plasmids (empty vector or expressing HA-mCherry) or plasmids expressing N-terminal HA tagged NMT1 or NMT2 before infection with MOPV (MOI 0.01)." (PMID 39625987, 2024). "We first showed that during infection the Z matrix protein interacted with NMT1 and NMT2, the enzymatic nature of this interaction rendering it likely difficult to grasp and detect." (PMID 39625987, 2024). "We measured mRNA levels of both enzymes in A549 cells and found that there was three to four times more mRNA encoding for NMT1 than NMT2 in cells regardless to the presence or the absence of infection, a result similar to observations in other cell lines." (PMID 39625987, 2024). "In the matching WB, the expression of NMT1 or NMT2 seemed constant across time and unaffected by infection." (PMID 39625987, 2024). "Lastly, miR-132 (NMT1-transcript-binding miRNA) and miR-29 (NMT2-transcript-binding miRNA) are involved in HIV infection, with the former promoting infection and the latter acting as an antiviral agent." (PMID 29579063, 2018). "Furthermore, miRNAs of interest may be overexpressed (gain-in-function) in cell lines through a lentiviral infection or plasmid transfection to determine their effect on NMT1/NMT2/METAP2 mRNA transcript levels using qPCR and the resulting protein expression by Western blot analysis." (PMID 29579063, 2018). "We then tested in identical condition of infection whether NMT1 and/or NMT2 were able to interact with the Z matrix protein during infection." (PMID 39625987, 2024). "We used lentiviral infection to generate Pan02 cell lines stably expressing control non-targeting shRNA or NMT1 shRNA along with GFP as a marker of infection." (PMID 27438140, 2016). "The fact that silencing the NMT1 and CKIIα genes blocked the infection of human cells by HIV-1 CRF02_AG but not clade-B viruses, suggests that the additional N-myristoylation and CKII domains present in Tat.AG sequences are functional and directly modulate the replication of CRF02_AG viruses." (PMID 31337802, 2019). "Both enzymes are present at the protein levels in our cellular extracts but we could not clearly differentiate the location of NMT1 and NMT2, nor evidence the location of their interaction with the Z matrix protein during infection." (PMID 39625987, 2024).
infectious disease (5 papers, 2013 to 2023). A disorder directly resulting from the presence and activity of a microbial, viral, or parasitic agent in humans. "We found 14 miRNAs that were associated with functions in infectious diseases, 8 of which target NMT1/2 genes and 6 miRNAs target MetAP2 gene." (PMID 29579063, 2018). "Lastly, 2 of each of the miRNAs targeting NMT1/2 were involved in infectious diseases, including HIV." (PMID 29579063, 2018). "Furthermore, miR-140, miR-628-3p and miR-943 miRNAs that target NMT1/2 and MetAP2 genes were found to have roles in infectious diseases." (PMID 29579063, 2018). "Specifically, studying miRNA interactions with the NMT1/2 and MetAP2 genes will shed light on the poorly understood regulation of myristoylation, a key cellular function critical to oncogenesis, adaptive immune function, and infectious disease onset." (PMID 29579063, 2018). "The association of microRNAs (miRNAs) that target N-myristoyltransferase (NMT) transcript 1 and 2 (NMT1 and NMT2) and MetAP transcripts with different infectious diseases and their expression changes." (PMID 29579063, 2018).
hematological cancer (3 papers, 2020 to 2024). "Databases analyses revealed that NMT2 expression levels varied significantly more than those of NMT1, and that hematologic cancer cell lines comprised the vast majority of the lowest NMT2 expressing cells." (PMID 38715059, 2024). "Third, it has been reported that the expression of the NMT2 gene is significantly decreased or even completely lost in certain hematological cancer types; hence, the development of a selective NMT1 inhibitor is of interest to the biotech industry." (PMID 36080246, 2022). "After describing the absence of NMT2 in most hematologic cancer cell lines and tumors, and their high sensitivity towards PCLX-001, we hypothesized that NMTI could exploit this loss by targeting the remaining NMT1 in an approach reminiscent of synthetic lethality." (PMID 38715059, 2024).
NMT1 also shares sentences with these, for which no sentence is quoted: human African trypanosomiasis (6 papers); Chagas disease (4); leishmaniasis (4); parasite infections (4); B-cell lymphomas (3); viral infection (3); oral squamous cell carcinoma (2); osteosarcoma (2); Stroke (2); trypanosomiasis (2); visceral leishmaniasis (2); bacterial infections (1); bipolar disorder (1); blood cancers (1); breast ductal carcinoma (1); cardiac hypertrophy (1); colorectal tumor (1); depression (1); diabetes (1); diffuse large B-cell lymphoma (1); essential hypertension (1); filariasis (1); follicular lymphoma (1); glioblastoma (1); hepatocellular carcinoma (1); HIV-1 infection (1); insomnia (1); iron deficiency (1); kidney cancer (1); leukemia (1).
A further 4 diseases each share a sentence with NMT1 in 1 paper.